TNF (tumor necrosis factor)
Diseases named in the same sentence as TNF in open-access papers (continued):
Sharing a sentence is not in itself a finding about the gene and the disease.
cervical carcinoma (173 papers, 2003 to 2026). A carcinoma arising from either the exocervical squamous epithelium or the endocervical glandular epithelium. "In summary, our pooled data indicated that the XRCC3 RS861539, TNF-α rs1800629, and IL-6 rs1800795 genetic variants were associated with susceptibility to cervical cancer globally." (PMID 34837895, 2021). "In the current study pooled data indicated that the TNF-α rs1800629 polymorphism was associated with cervical cancer risk." (PMID 34837895, 2021). "SNPs within the TNF region were significantly associated with the risks of vulvar cancer and cervical cancer." (PMID 34683414, 2021). "There was a significant association between XRCC3 RS861539, TNF-α rs1800629, and IL-6 rs1800795 polymorphisms and an increased risk of cervical carcinoma in overall population." (PMID 34837895, 2021). "CK2 function is directly associated with TNF-α and p38 signaling to mediate inflammatory processes as demonstrated in context of stress-induced human cervical carcinoma cells and diabetic retinopathy in retinal ECs." (PMID 33178683, 2020). "The GO and KEGG pathway analyses revealed that these differentially expressed miRNAs are tightly associated with cervical cancer tumorigenesis, through interaction with the Notch signaling pathway, TNF signaling pathway, and TGF-β signaling pathway." (PMID 32596357, 2020). "TNF-α-308G > A can increase the susceptibility of cervical cancer, while TNF-α-238G > A can significantly decrease its susceptibility." (PMID 25928231, 2015). "For example, in studies of the relationship between TNF-α-308G > A with the pathogenesis of cervical cancer, Duarte I found that this SNP is significantly associated with cervical cancer (OR = 1.8, 95% CI [1.21, 2.69])." (PMID 25928231, 2015). "To identify the miR-130a target genes responsible for its effects on cervical cancer cells, we used bioinformatics and functional knowledge associated with NF-κB and miR-130a and chose TNF-α as a candidate gene for further study." (PMID 24885472, 2014). "Subgroup analysis by the types of cervical lesions showed that there was a significant association between TNF-α rs1800629 polymorphism and increased risk of cervical cancer." (PMID 24015171, 2013). "Large prospective studies with matched case-control studies are needed to better elucidate the precise role of the TNF rs1800629 polymorphism in cervical cancer." (PMID 23028877, 2012). "Several investigators have studied the polymorphisms within the TNF-α promoter region to estimate the immune responses to a wide range of cancers including cervical cancer." (PMID 16438713, 2006). "Odds Ratios and 95% confidence intervals (CI) for the development of cervical cancer in relation to -308 TNF-α alleles among the cervical cancer cases and controls in the two South African ethnic population groups." (PMID 16438713, 2006). "Numerous studies have investigated the association between the effect of TNF-α promoter region and cervical cancer, but the results have been contradictory." (PMID 16438713, 2006). "Moreover, TNF-308 AA and IL-10-592 CA/AA polymorphisms are linked to an increased risk of cervical cancer." (PMID 37704909, 2023). "Similarly, various polymorphic sites of the tumor necrosis factor (TNF) genes have been associated with an increased risk of cervical cancer." (PMID 34960724, 2021). "Among those 20 studies, most studies 17 studies (85.0%) were about the association between TNF-α rs1800629 polymorphism and invasive cervical cancer, while the left 3 ones were about the association between TNF-α rs1800629 polymorphism and squamous intraepithelial lesions." (PMID 24015171, 2013). "Further complexity for the TNF-α effect on cells is caused by HPV viruses in cervical carcinomas." (PMID 18257926, 2008). "Therefore the aim of the study was to investigate the allelic distribution of -308 TNF-α gene polymorphism in South African women with cervical cancer compared to control women." (PMID 16438713, 2006).
cervical carcinoma (continued). "Thus in the present study we sought to identify the possible link between -308 A/G TNF-α allele polymorphism and the progression of cervical cancer among two ethnic population groups in South Africa." (PMID 16438713, 2006). "In this context, our findings of lower risk of cervical cancer after PE suggest that immune regulation in these women, such as elevated TNF-α, IL-6, and IL-7 responses along with enhanced cytotoxic T-cell activation, might reduce the risk of persistent HPV infection." (PMID 40610749, 2025). "In addition, several studies have indicated that the polymorphisms in the promoter region of -308 TNF-α may be a contributing factor for the development of cervical cancer." (PMID 16438713, 2006). "Cytokines such as IL-6 and TNF-α are pivotal mediators of the inflammatory microenvironment in cervical cancer, yet their roles are complex and context-dependent." (PMID 41497141, 2026). "One of the primary mechanisms of cytokine storm in cervical cancer is the excessive release of cytokines such as IL-6, TNF-α, IL-1β, and IL-8." (PMID 41497141, 2026). "Several lines of evidence support the potential of specific biomarkers (such as cancer antigen 125, soluble form of interleukin 2 receptor, and tumor necrosis factor for identifying early‐stage cervical cancer and providing patients with a better prognosis)." (PMID 41204766, 2025). "GO and KEGG enrichment analysis of key targets predicted the cancer pathway, PI3K-AKT-MDM2 expression pathway, VEGFA signaling pathway, and TNF signaling pathway for cervical cancer." (PMID 40238841, 2025). "Therefore, the primary objective of this study was to investigate whether DHC enhances TNF-α-induced G1 cell cycle arrest and apoptosis in human cervical cancer HeLa cells and to elucidate the underlying molecular mechanisms, particularly focusing on the TAK1-NF-κB and MAPK-EGFR signaling pathways." (PMID 40507823, 2025). "Studies indicate that abnormal concentrations of TNF-α suggest its critical role in the molecular pathogenesis of cervical carcinoma and offer a potential biomarker for the early diagnosis and therapy of the disease." (PMID 40136934, 2025). "It has been found that the malignancy of cervical cancer is positively correlated with cellular TNF expression, and therefore, cellular TNF-α expression can be used as an observational index for cervical cancer grading as well as prognosis." (PMID 40238841, 2025). "Our study demonstrates that dihydrocapsaicin (DHC) significantly enhances TNF-α-induced G1 cell cycle arrest and apoptosis in HeLa cervical cancer cells by targeting the TAK1-mediated NF-κB and EGFR survival pathways." (PMID 40507823, 2025). "Four genes associated with survival of cervical cancer patients were selected by survival by univariate analysis: EGFR, TNF-α, VEGFA and MDM2 (P<0.1)." (PMID 40238841, 2025). "In the multivariate Cox regression, N1 stage, high-risk score, and the genes TNF, ITGA5, CXCL1, and CCL20 were observed to be significantly associated with increased risk in cervical cancer patients." (PMID 40517358, 2025). "MiR-21 was up-regulated and regulated multiple signaling pathways in cervical cancer, including TNF-α/caspase-3/caspase-8, PI3K/AKT/mTOR, and RAS/MEK/ERK pathways." (PMID 39060960, 2024). "It correlated with the enhanced cytotoxicity of co-cultured T lymphocytes toward HeLa, SiHa and CaSKi cervical cancer cells and higher production of TNF-α and ITF-γ by T cells." (PMID 39457512, 2024). "Valproic acid (VPA) exhibits time-dependent inhibition of HIF-1α, VEGF, and tumor necrosis factor (TNF) expression in cervical cancer cells through suppression of PI3K/Akt and ERK1/2 signaling pathways." (PMID 39435279, 2024). "In our study, we observed that the expression of VEGFC was significantly increased in the CM collected from the TNF-α-treated cervical cancer cells." (PMID 37124061, 2023).
cervical carcinoma (continued). "A refined risk score model, comprising PLA2G7, TNF, TYK2, F2, and NRP1, effectively stratified cervical cancer patients into distinct risk groups." (PMID 37704909, 2023). "The present work shows evidence that PTX decreased TNF-α/TGF-β1-induced EMT in cervical cancer cells via NF-κB and TGF-β1/Smad pathways." (PMID 37445768, 2023). "In the present study, the CM collected from the TNF-α-treated cervical cancer cells was found to increase p-AKT and p-ERK expressions in HLECs." (PMID 37124061, 2023). "In conclusion, our studies, to our knowledge for the first time, provided evidence of the antimetastatic activity of PTX in counteracting TNF-α/TGF-β1-induced EMT in cervical cancer cells via the NF-κB/TGF-β1/SERPINE1." (PMID 37445768, 2023). "By using a non-replicative virus, we observed a 2- to 10-fold increase in promoter activity under hypoxia and TNFα (as an activator of the NFkB elements of the promoter) in human cervical cancer cell lines." (PMID 37373140, 2023). "With the aim of investigating the effect of TNF-α on the formation of lymphangiogenesis in cervical cancer, HLECs were cultured in CM-TNF-α." (PMID 37124061, 2023). "This work aimed to evaluate the effect of PTX in the EMT induced by TNF-α/TGF-β1 in CaSki human cervical cancer cells and their possible mechanisms." (PMID 37445768, 2023). "A reduced expression of E-cadherin was reported as a result of TGF-β treatment of cervical cancer cells, TNF-α treatment, IL-6 treatment, and treatment with Chemokine (C–C motif) ligand 20 (CCL20)." (PMID 36766756, 2023). "The aim of the present study was therefore to investigate the mechanism through which TNF-α regulates lymphatic microvessel formation in cervical cancer." (PMID 37124061, 2023). "Although the direct target is yet to be known, research has shown that microRNA-21 indirectly upregulates TNF-α level in cervical cancer cell lines." (PMID 35895593, 2022). "constructed a new prognosis predication model based on 8 risk-related PRGs (GPX4, GSDME, GZMA, GZMB, IL1B, NOD1, PRKACA, and TNF) in cervical cancer, which had good predictive ability (AUC = 0.794)." (PMID 35912258, 2022). "Although DAPK serves an important role in a wide array of apoptotic signals, including IFN-γ, TNF-α, Fas, activated c-Myc and detachment from extracellular matrix 8, its proapoptotic role in certain tumor types, such as cervical cancer, remains elusive." (PMID 35154442, 2022). "HPV-16 VLPs stimulate plasmacytoid DC responses such as releasing cytokines like IL-6, interferon alpha (IFN-α), and tumor necrosis factor alpha (TNF-α) in cervical cancer." (PMID 36276117, 2022). "NK cells have been found to fight against cervical cancer through the secretion of tumor necrosis factor-alpha (TNF-α) and interferon-gamma (IFN-γ)." (PMID 36139618, 2022). "In this meta-analysis, we explore the role of XRCC3 rs861539, MTHFR rs1801133, IL-6 rs1800795, IL-12B rs3212227, TNF-α rs1800629, and TLR9 rs352140 polymorphisms in susceptibility to cervical cancer." (PMID 34837895, 2021). "Here we compared FHL124 cells and HeLa cells, spontaneously immortalized epithelial cell lines derived from the human lens and cervical cancer cells, respectively, of their resistance to TNFα-mediated cell death." (PMID 33837174, 2021). "In this meta-analysis, the association of XRCC3 rs861539, MTHFR rs1801133, IL-6 rs1800795, IL-12B rs3212227, TNF-α rs1800629 and TLR9 rs352140 polymorphisms with susceptibility to cervical carcinoma was assessed by including all relevant studies." (PMID 34837895, 2021). "We performed this meta-analysis to explore the role of XRCC3 rs861539, MTHFR rs1801133, IL-6 rs1800795, IL-12B rs3212227, TNF-α rs1800629 and TLR9 rs352140 polymorphism with susceptibility to cervical carcinoma." (PMID 34837895, 2021).
cervical carcinoma (continued). "The predominant pathogen of AV can decrease the beneficial effects of lactobacillus, causing inflammation, such as increased levels of IL-6, IL-8 and TNF-α, increasing the risk of HPV 16 infection which results in CIN or cervical cancer." (PMID 32605571, 2020). "In tumor necrosis factor-alpha-stimulated human cervical cancer HeLa cells, miR-4454 was identified as an NF-κB-targeting miRNA, with roles in the anti-inflammatory, apoptosis, and other physiological processes of cervical cancer cells." (PMID 32816024, 2020). "In the present study, we found that, [Cu(PMPP-SAL)(EtOH)] exhibited a growth-inhibiting effect on the proliferation of TNF-α-stimulated cervical cancer cells." (PMID 33106514, 2020). "HPV16-E6 and E7 proteins repress basal and TNF-α-inducible NF-kB activity in cervical cancer cells, promoting onset of cervical cancer." (PMID 32695664, 2020). "LOC105374902 induced by TNF-α, a multiple functional cytokine which can regulate inflammation and immunity of cancer, was found to promote the malignant behavior of cervical cancer cells by acting as a sponge of miR-1285-3p." (PMID 33274204, 2020). "Recent data demonstrated that TNF-α was downregulated at both mRNA and protein levels in cervical cancer and in CIN cases compared to controls." (PMID 30847024, 2019). "In this study, we discovered that two cervical cancer cell lines, Hela and Siha, showed null responses to TNF‐α cytotoxicity." (PMID 29632814, 2018). "The experimental data showed that blocking endogenous miR‐130b produced a decrease in the viability of vehicle‐treated cervical cancer cell, but more reduction in the viability was observed in TNF‐α‐treated counterpart." (PMID 29632814, 2018). "In this study, we found that the expression of miR‐130b was promoted by TNF‐α treatment in cervical cancer cell but the increased expression of miR‐130b affected the TNF‐α cytotoxicity in a negative way." (PMID 29632814, 2018). "As it was proved that TNF‐α stimulation increased the level of miR‐130b in cervical cancer cell, we assumed that miR‐130b must participate in the regulation of reporter gene." (PMID 29632814, 2018). "A meta-analysis study showed that the A/A genotype frequency of TNF-α in cervical cancer cases and controls was 0.97%~7.33% and 0%~6.78%, respectively." (PMID 29951534, 2018). "We tried to gain insight to the mechanism underlying this phenomenon through our study and demonstrated that the inhibition of miR‐130b function enhanced the TNF‐α‐induced cell death of cervical cancer cell." (PMID 29632814, 2018). "In our study, we discovered that TNF‐α stimulation brought about the attenuation in the level of PTEN mRNA as well as protein in cervical cancer cell." (PMID 29632814, 2018). "These experimental data suggested that cervical cancer cells should develop their resistances to TNF‐α cytotoxicity by suppressing the expression of PTEN gene." (PMID 29632814, 2018). "Enhanced the antioxidant enzyme activities, and reduced levels of IL-1b, IL-6, and TNF-α in rats with cervical cancer." (PMID 30410443, 2018). "The TNF-α A/A genotype significantly elevating risks of cervical cancer was found in a Caucasian population (OR: 2.09, 95% CI: 1.34~3.25)." (PMID 29951534, 2018). "The data suggested these cervical cancer cells resistant to the toxicities mediated by TNF‐α at these concentrations." (PMID 29632814, 2018). "The first detailed study was conducted using the RNAi system and showed that Prx III inhibits the mitochondrial mPT and cytochrome c release in HeLa cervical cancer cells treated with tumor necrosis factor (TNF)-α and staurosporine." (PMID 30423872, 2018). "STAT1/IRF-1 pathways initiated by IFNγ had been shown to be important in TNFα and IFNγ synergism in inducing cervical cancer cell apoptosis." (PMID 27342639, 2016).
cervical carcinoma (continued). "We observed mice tumor inhibition rate and conducted the histopathological analysisUsing the western blot assay, the expression of TGF-β1 and TNF-α protein in transplanted cervical cancer U27 tumor tissue were detected." (PMID 27881109, 2016). "In our experiment, different SMEDDS compositions were also investigated in the presence of IL-1-β and TNF-α on human cervical cancer HeLa cells." (PMID 26197311, 2015). "Through this method, the relationship of some SNPs, such as TNF-α-308G > A and TNF-α-238G > A, associated with cervical cancer has been proven." (PMID 25928231, 2015). "We observed the striking ability of TIMP-4 to enhance apoptosis in cervical cancer cell lines after death receptor ligand (TNF-α and TRAIL) treatment and serum starvation." (PMID 26291714, 2015). "It was reported that TNF-α would be highly increased in cervicovaginal washings from patients with cervical carcinoma." (PMID 24683359, 2014). "We showed here that KIAA1199 protects from cell death triggered by Semaphorin 3A or by TNFα in cervical cancer cells." (PMID 25366117, 2014). "This study is the first to demonstrate that NF-κB and miR-130a can promote the growth of human cervical cancer cells and identifies TNF-α as a new target gene of miR-130a." (PMID 24885472, 2014). "Based on these results, we provide evidence of the existence of an NF-κB/miR-130a/TNF-α/NF-κB feedback loop in cervical cancer cells." (PMID 24885472, 2014). "The findings from the meta-analysis suggest that TNF-α rs1800629 polymorphism is associated with increased risk of cervical lesions and TNF-α plays an important role in the development of cervical cancer." (PMID 24015171, 2013). "Increased expression of TNF-α has been observed in association with HPV infection in both normal cervical tissues and cervical cancers, supporting the importance of TNF-α in response to HPV and to subsequent carcinogenesis." (PMID 23870134, 2013). "The aim of this study was to investigate the relationship between the TNF-alpha rs1800629 polymorphism and risk of HPV infection or cervical cancer." (PMID 23028877, 2012). "And in the progression of multiple factors induced cancer, the duality of TNF-α determine that it doesn't have decisive influence in cervical cancer." (PMID 23028877, 2012). "HPV-harboring cervical keratinocytes constitutively produce active TNF-α, whereas cervical cancer cell lines or cervicovaginal washing fluid from patients with cervical neoplasia all have high levels of TNF-α." (PMID 23554684, 2011). "Previously, chemotactic migration of SiHa and CaSki cervical carcinoma cell lines to laminin-1 has been shown to be significantly decreased by TNF-α while migration towards type I collagen was increased." (PMID 18257926, 2008). "Conversely, it has been reported that TNF exerts a potent cytostatic effect on HPV16-immortalized keratinocytes while HPV18-immortalized as well as cervical carcinoma-derived HPV-positive cell lines remain unaffected." (PMID 18588690, 2008). "TNF-α expression in 8 cervix carcinoma samples was semiquantitatively analyzed and compared to that in 10 control samples with nonspecific inflammatory changes." (PMID 18257926, 2008). "Since SiHa cells showed only weak TNFRI and II immunostaining these receptors as well as TNF-α were stained also in cervical carcinoma specimens." (PMID 18257926, 2008). "This study examined the effect of the selective COX-2 inhibitor celecoxib on cisplatin and TNF-α cytotoxicity and studied the role of mitochondria in the induction of apoptosis in the human cervical carcinoma SiHa cells." (PMID 23675041, 2007). "Many natural and synthetic compounds have been shown to modulate cisplatin and TNF-α mediated cytotoxicity in human cervical carcinoma cells." (PMID 23675041, 2007). "In the present study we investigated the enhancement of cytotoxic effects of cisplatin and TNF-α by selective COX-2 inhibitor celecoxib on human cervical cancer cells." (PMID 23675041, 2007).